BRCA2 (BRCA2 DNA repair associated)
Diseases named in the same sentence as BRCA2 in open-access papers (continued):
Sharing a sentence is not in itself a finding about the gene and the disease.
breast cancer (continued). "Although identification of BRCA1 and BRCA2 has greatly increased the understanding in breast cancer genetics in Western populations but the role of these genes for developing breast cancer in the Bangladeshi population still remains unexplored." (PMID 32856854, 2020). "Like BRCA1 and BRCA2 gene mutations, PALB2 mutations are also associated with high risk of breast cancer." (PMID 32824813, 2020). "In breast cancer patients, the tumor phenotype differs according to the BRCA1 or BRCA2 germline mutation status." (PMID 32341426, 2020). "In breast cancer, pioneering work in risk prediction, modelling genetic susceptibility based on two genes, BRCA1 and BRCA2, has been expanded to the use of polygenic scores, which have improved predictive ability." (PMID 32423490, 2020). "Genetic alterations in the breast cancer 1 (BRCA1) and breast cancer 2 (BRCA2) pathway comprise the largest number of relevant genomic alterations in high-grade ovarian serous cancers (HGSCs)." (PMID 32403357, 2020). "Using data from The Cancer Genome Atlas (TCGA) for 1101 breast-cancer patients, we identified individuals with a germline mutation, somatic mutation, homozygous deletion, and/or hypermethylation event in BRCA1, BRCA2, and 59 other cancer-predisposition genes." (PMID 32997669, 2020). "In 2005, two seminal papers were published demonstrating that breast cancer cells with siRNA depletion of BRCA1 or BRCA2 were exquisitely sensitive to the PARP inhibitor NU1025." (PMID 32183301, 2020). "Germline pathogenic alterations in the breast cancer susceptibility genes 1 (BRCA1) and 2 (BRCA2) are the most prevalent causes of hereditary breast and ovarian cancer." (PMID 32655641, 2020). "We successfully amplified and sequenced the exons of BRCA1 and BRCA2 in seventy breast cases with breast cancer and/or ovarian cancer family history, and a total of 48 variants were detected in discovery stage." (PMID 32879886, 2020). "In vitro and vivo findings have demonstrated PARG depletion is a common occurrence in PARPi resistant BRCA2-deficent mouse mammary tumor models." (PMID 33015058, 2020). "Rhiem further observes that patients diagnosed with breast cancer at age <40 years had a cumulative risk 25 years from primary diagnosis of 55.1% and 38.4% for BRCA1 and BRCA2-positive family history, respectively." (PMID 31935898, 2020). "Bilateral breast cancer and ovarian and prostate cancers are thought to be associated with pathogenic variants in the BRCA1 and BRCA2 genes." (PMID 31965555, 2020). "A third report indicated a total deletion of exons 1–27 of BRCA2 and exons 1–27 of RB1 indicating increased risk of breast cancer and retinoblastoma, respectively." (PMID 32377377, 2020). "This occurrence likely facilitated the African American breast cancer associations regarding ATM c.2289T>C (p.F763L), BRCA2 c.2926_2927delinsAT (p.S976I) and RAD51D c.251T>A (p.L84H)." (PMID 32866190, 2020). "BRCA1, BRCA2, and PALB2 are established breast cancer predisposition genes conferring high risk especially for ER-negative disease and TNBC." (PMID 31991861, 2020). "Discovery of the breast cancer 1 (BRCA1) and breast cancer 2 (BRCA2) genes led to the development of genetic tests to identify individuals at risk for hereditary breast and ovarian cancer (HBOC)." (PMID 31963545, 2020). "The HRs for the breast cancer association decreased with age (PRS-by-age interaction HRs: BRCA1 HR = 0.996, P = 0.003; BRCA2 HR = 0.994, P = 9.40×10−5)." (PMID 32665703, 2020).
breast cancer (continued). "The BRCA1 and BRCA2 genes are directly related to hereditary breast cancer, and are more frequently present in patients with a family history of breast cancer." (PMID 33257598, 2020). "In the case of breast cancer, the surveillance follow-up should copy that in BRCA1/BRCA2 mutation carriers." (PMID 33322746, 2020). "Variants in the breast cancer susceptibility genes BRCA1 and BRCA2 increase the risk of developing breast and ovarian cancers." (PMID 33081408, 2020). "To date, BRCA1, BRCA2, PTEN, ATM, and CHEK2 have been sequentially reported as medium-to-high penetrant genes associated with breast cancer risk." (PMID 32879886, 2020). "Mutation in either BRCA2 or PALB2 is associated with reducing the ability of cells in HR repairing and accordingly, increasing the risk of breast cancer." (PMID 33013205, 2020). "The majority of the BRCA2-related breast cancers are hormone receptor positive, and rely on the endogenous supply of estrogen and possibly progesterone for proliferation." (PMID 32964118, 2020). "As it has now been established that LOF variants in PALB2 convey a similarly high risk for breast cancer as BRCA2 LOF variants, PALB2 has become widely included in breast cancer clinical genetics practice." (PMID 33195396, 2020). "On the other hand, the onset age of breast cancer from BRCA2 carriers is 10 years older than that of breast cancer from BRCA1 carriers and is highly associated with estrogen receptor (ER) positive breast cancer." (PMID 33167385, 2020). "Of 993 breast-cancer patients with available germline data, 22 harbored a pathogenic SNV or indel in BRCA1; 22 harbored a BRCA2 variant." (PMID 32997669, 2020). "The estimated risk up to 80 years of age for ovarian and breast cancer among women with BRCA1 and BRCA2 pathogenic germline gene variants is 44 and 72% respectively for BRCA1 and 17 and 69% respectively for BRCA2." (PMID 32165993, 2020). "Around 5–10% of breast cancers are caused by an inherited faulty genes such as the BRCA1 and BRCA2 genes (Cancer Research UK 2014; Cancer Research UK 2018a, b)." (PMID 31965555, 2020). "All of the women had a history of breast cancer, with a large portion of them being BRCA1 or BRCA2 mutation carriers." (PMID 32722165, 2020). "The observation of familial clustering of breast cancer and subsequent identification of heritable risk attributable to BRCA1 and BRCA2 has had broad impact on risk prediction, precision care, and etiological understanding." (PMID 32251286, 2020). "Nevertheless, pathogenic mutations in the breast cancer susceptibility genes BRCA1 and BRCA2 only account for 25–40% of familial breast cancers (FBCs) cases." (PMID 32300589, 2020). "The corresponding absolute risks for BRCA2 carriers by age 50 years ranged from 23% to 49% and by age 80 years from 57% to 81% for breast cancer." (PMID 32665703, 2020). "Pathogenic variants in the two most well‐known high‐risk breast cancer genes, BRCA1 and BRCA2, explain approximately 17% of the familial relative risk." (PMID 32383162, 2020). "BRCA1 and BRCA2 genes are currently proven to be closely related to high lifetime risks of breast cancer." (PMID 31998560, 2020). "Several FA genes, such as BRCA1/FANCS, BRCA2/FANCD1, PALB2/FANCN, and RAD51C/FANCO have been confirmed to be breast carcinoma susceptibility genes at present." (PMID 32300589, 2020).
breast cancer (continued). "Approximately 10% of all breast cancer (BC) cases are familial and caused by inheritance of mutant BRCA1, BRCA2, or some other genes from the same DNA reparation pathway." (PMID 32164353, 2020). "BRCA2 breast carcinomas are most closely like sporadic tumors, generally expressing the estrogen receptor (77%) and are in the minority triple negative." (PMID 32481735, 2020). "The histology of breast cancers in women predisposed by BRCA1 and BRCA2 mutations differs in several ways." (PMID 32411603, 2020). "While most breast cancers carrying BRCA1 mutations undergo loss-of-heterozygosity (LOH) of their wild-type allele as their second hit, BRCA1 and BRCA2 promoter methylation have also been detected in some tumors without LOH." (PMID 31225507, 2019). "BRCA2 carriers were significantly less likely to be ever users of hormone replacement therapy (HRT) than non‐BRCA breast cancer patients (26.2% vs 53.8%) (eTable 6 in Data Supplement 1)." (PMID 30175445, 2019). "In the present study on 27 families with male breast cancer, a BRCA1/2 mutation frequency of approximately 19% was observed, with BRCA2 mutations being about 4-times more common than BRCA1 mutations." (PMID 31528241, 2019). "One prospective cohort study evaluating over 9,000 mutation carriers, the majority from Europe, found the cumulative breast cancer risk to age 80 years was 72% for BRCA1 and 69% for BRCA2 carriers." (PMID 30915162, 2019). "The presence of bilateral breast cancer (BBC), number of BC cases and the presence of ovarian cancer (OC) increased (respectively) 5.797, 5.033 and 4.412 times the risk of being a BRCA1/BRCA2 mutation carrier." (PMID 31244284, 2019). "In a large collection of families with hereditary breast cancer (n=237), 52% of families had disease that was likely attributable to mutations in BRCA1 while 32% had disease linked to BRCA2." (PMID 31379942, 2019). "Numerous studies have revealed mutational signatures associated with breast cancer, namely signatures 1, 2, 3, 8, and 13, and also provide a mutational characterization of cancers with BRCA1 and BRCA2." (PMID 30934991, 2019). "Genes such as BRCA1 and BRCA2 are even named after particular subtypes of breast cancer, indicating their unequivocal genetic contribution." (PMID 31480430, 2019). "To address this issue, we aimed to investigate the differences in AAO of breast cancer among BRCA1 mutation carriers by studying 311 DNA-repair genes which are contributing to genome stability along with BRCA1 and BRCA2." (PMID 31395037, 2019). "Over the last two decades, discoveries related to the breast cancer susceptibility genes 1 and 2 (BRCA1 and BRCA2) have profoundly changed our understanding and management of hereditary breast and ovarian cancers." (PMID 30915162, 2019). "There were 49 DCIS in 325 breast cancers, and nine cases out of sixty‐two BRCA mutation were DCIS, 2% (n = 1) carried a BRCA1 mutation, and 16.4% (n = 8) carried a BRCA2 mutation." (PMID 30652428, 2019). "In a large study, they found that for BRCA1 PV carriers, the PRS model that predicted ER-negative breast cancers was more predictive than the overall breast cancer model that was more predictive in BRCA2 PV carriers." (PMID 30832243, 2019). "Genetic screens are increasingly being offered for the identification of pathogenic variants, which increase the risk of developing breast cancer, in BRCA1, BRCA2 and other breast cancer genes." (PMID 30832243, 2019).
breast cancer (continued). "For instance, themes of DNA repair and G2‐M checkpoint regulation are consistent with the known roles of BRCA1/BRCA2 and ATM proteins, which are established risk factors for breast cancer." (PMID 30872331, 2019). "A germline mutation in BRCA1 or BRCA2 genes is known to be associated with a much higher than average lifetime risk (72% for BRCA1 and 69% for BRCA2 mutation carriers) of developing breast cancer." (PMID 31182087, 2019). "Compared to the general population, the risk of breast cancer in BRCA1 and BRCA2 mutation carriers increases by 10‐ to 20‐fold (Ludwig, Neuner, Butler, Geurts, & Kong, 2016; Nelson, Huffman, Fu, Harris, & U.S. Preventive Services Task Force, 2005)." (PMID 30968603, 2019). "In BRCA2 carriers, these effects are mainly observed in the first 3–5 years as they typically present with ER+ positive breast cancer and benefit from the immediate hormone deprivation." (PMID 31267556, 2019). "The identification of deleterious mutations in the breast cancer susceptibility genes BRCA1 and BRCA2 has important implications for mutation carriers in general, because they are the principal cause of Hereditary Breast and/or Ovarian Cancer Syndrome." (PMID 30652428, 2019). "Approximately 15–40% of hereditary breast cancers occur due to pathogenic variants (PVs) of BRCA1 (17q21) and BRCA2 (13q12–13)." (PMID 31331294, 2019). "Genetic linkage studies have identified BRCA1 (OMIM# 113705) and BRCA2 (OMIM# 600185) as two major genes associated with hereditary breast cancer and high breast cancer risk." (PMID 31131559, 2019). "Fifty-nine breast cancers met selection criteria; of these, 30 were BRCA1-associated tumors, and 29 were BRCA2-associated tumors." (PMID 30820924, 2019). "A proportion of all breast cancers can be explained by the inheritance of germline mutations in one of the two major breast cancer susceptibility genes BRCA1 and BRCA2 related to DNA repair mechanisms." (PMID 30842790, 2019). "A BRCA1 mutation can be detected in 52% of breast cancer patients and up to 80% have a mutation in either BRCA1 or BRCA2." (PMID 31182966, 2019). "Hereditary breast and ovarian cancers are primarily related to highly penetrant germline mutations in either one of the two breast cancer susceptibility genes, BRCA1 and BRCA2." (PMID 30915162, 2019). "Therefore, further validation in study populations consisting of higher proportion of BRCA1- and BRCA2-deficient breast cancers, such as that in breast cancer cohorts enriched with a prior high-risk patients, may be warranted to assess the generalizability of our findings." (PMID 31022191, 2019). "Breast cancer risk is slightly higher among women of Ashkenazi Jewish descent than among other women, likely due to the high prevalence of BRCA1 and BRCA2 pathogenic or likely pathogenic variants in this population." (PMID 30759220, 2019). "The results showed that an increased expression of BRCA2 was detected in low-methylated BRCA2 breast cancer samples (P = 0.037)." (PMID 31506496, 2019). "Germline pathogenic variants in DNA repair genes BRCA1, BRCA2, PALB2, ATM, and CHEK2 are associated with breast cancer risk." (PMID 31700994, 2019). "The DNA- associated proteins BRCA1 and BRCA2 (Breast Cancer 1 and 2) also play an important role in DNA break repair and recombination in association with PALB2 (Partner and Localizer of BRCA2)." (PMID 30995915, 2019). "We have previously shown that mammary tumours in a Brca2-mutant mouse model generally respond well to olaparib, but that eventually tumours relapse on treatment." (PMID 31080552, 2019). "A number of countries other than Japan have previously conducted studies that demonstrated differences in histopathology and imaging characteristics between breast cancers associated with BRCA1 and BRCA2 mutations." (PMID 30820924, 2019).
breast cancer (continued). "In breast cancer patients, a more severe phenotype has been reported in individuals with double heterozygosity for disease-causing BRCA1 and BRCA2 mutations, two genes of the Fanconi anemia/Breast cancer pathway." (PMID 30305723, 2019). "In cancer predisposition genes, there are 25 globally known SNPs identified to increase risk of breast cancer and of the 25, 14 SNPs are located in BRCA1 and BRCA2 genes." (PMID 31131559, 2019). "We examined the association between regular NSAID use and breast cancer risk using a large cohort of women selected for breast cancer family history, including 1054 BRCA1 or BRCA2 mutation carriers." (PMID 30999962, 2019). "BRCA1 (breast cancer, early onset 1) and BRCA2 (breast cancer, early onset 2) are essential components of the homologous recombination (HR) DNA repair machinery, which repairs toxic DNA double‐stranded breaks (DSBs)." (PMID 31529615, 2019). "Prevalence rates are also high among certain ethnicities; 10%–12% of breast cancers in the Ashkenazi Jewish population, unselected for family history, are attributable to mutations in BRCA1 or BRCA2." (PMID 30915162, 2019). "The significant contribution of additional genes, other than BRCA1 and BRCA2, was also observed in breast cancer patients." (PMID 31159747, 2019). "In 1994 and 1995, the first genes associated with susceptibility to breast cancer, BRCA1 (OMIM # 113705) and BRCA2 (OMIM # 600185), were identified." (PMID 31341521, 2019). "Overall, as previous studies showed 3%–28% of familial breast cancer cases are linked to variants in BRCA1 and BRCA2 genes." (PMID 31131559, 2019). "In contrast, the CN profiles of the 16 BRCA2 breast cancers with bi-allelic inactivation were more similar to those of the PALB2-associated breast cancers, albeit more frequently harboring losses of 13q and 22q, among other differences (P < 0.05)." (PMID 31428676, 2019). "Male breast cancer (MBC) incidence is less than 0.001% and the penetrance of male BRCA2 mutation carriers is 5–10% for BC." (PMID 30940775, 2019). "We conclude that the breast cancer risk association of these two FANCC variants, if any, is much smaller than for BRCA1, BRCA2 or PALB2 mutations." (PMID 31467304, 2019). "While most hereditary cases of breast cancer are associated with pathogenic variants in BRCA1 and BRCA2, less common variants in other genes have also been associated with increased risk of developing breast cancer." (PMID 30759220, 2019). "Pathogenic variants associated with hereditary breast cancer have been reported for BRCA1 and BRCA2 (BRCA1/2) genes in patients from multiple ethnicities, but limited information is available from sub-Saharan African populations." (PMID 31060517, 2019). "Only a relatively small proportion of breast cancers can be explained by the presence of high-penetrance genetic mutations, such as those in the BRCA1 and BRCA2 genes." (PMID 30781715, 2019).